SEMA4B (semaphorin 4B)
Description:
Inhibits axonal extension by providing local signals to specify territories inaccessible for growing axons.
Synonyms: KIAA1745; SEMAC; SemC; MGC131831
Tractability: Antibody: UniProt predicts a signal peptide or a membrane-spanning region; its Gene Ontology location is reachable by antibodies, with medium confidence. PROTAC: ubiquitination databases record sites on it; its protein half-life has been measured.
Gene: Protein-coding gene on chromosome 15 (90,160,604 to 90,229,679, forward strand). Ensembl gene ENSG00000185033.
Subcellular location: Membrane
Subcellular location (Human Protein Atlas): Cell Junctions; Nucleoplasm; Vesicles
Gene Ontology:
Molecular function: protein binding; chemorepellent activity; neuropilin binding; semaphorin receptor binding
Biological process: axon guidance; negative chemotaxis; neural crest cell migration; positive regulation of cell migration; semaphorin-plexin signaling pathway
Cellular component: plasma membrane; glutamatergic synapse; membrane; postsynaptic density membrane; synapse
Genetic constraint (gnomAD): Loss-of-function variants: 54 observed, 76.72 expected, observed/expected ratio (o/e) 0.7, 90% interval 0.56 to 0.88. The upper end of that interval is the gene's LOEUF score, 0.88, which puts it in group 3 of 6, group 1 being the genes least tolerant of losing a copy. Missense variants: 1,058 observed, 1,046.3 expected, observed/expected ratio (o/e) 1.01, 90% interval 0.96 to 1.06. Synonymous variants: 525 observed, 449.72 expected, observed/expected ratio (o/e) 1.17, 90% interval 1.09 to 1.25.
Homologues: Orthologues: chimpanzee SEMA4B (98% identical), macaque SEMA4B (96% identical), pig SEMA4B (86% identical), dog SEMA4B (86% identical), rat Sema4b (83% identical), mouse Sema4b (83% identical), rabbit SEMA4B (82% identical), guinea pig SEMA4B (81% identical), tropical clawed frog sema4b (56% identical), zebrafish sema4ba (50% identical), zebrafish sema4bb (49% identical). Paralogues in human: SEMA4D (35% identical), SEMA4C (35% identical), SEMA4A (34% identical), SEMA4G (33% identical), SEMA4F (30% identical), SEMA3B (27% identical), SEMA3A (27% identical), SEMA6B (26% identical), SEMA3F (26% identical), SEMA5B (26% identical), SEMA3G (25% identical), SEMA6A (25% identical), and 7 more.
Diseases named in the same sentence as SEMA4B in open-access papers:
SEMA4B is named in the same sentence as 45 diseases in open-access papers, as found by Europe PMC text mining. Sharing a sentence is not in itself a finding about the gene and the disease. The quoted sentences say what the papers report.
breast cancer (8 papers, 2019 to 2025). A primary or metastatic malignant neoplasm involving the breast. "CircSEMA4B inhibits the proliferation, migration, and invasion of breast cancer cells by encoding the SEMA4B-211aa protein and can also act as an miR-330-3p sponge to upregulate the expression of the tumor suppressor gene PDCD4." (PMID 36768607, 2023). "CircSEMA4B was proven to be downregulated in breast cancer tissues and to play a negative regulatory role in the PI3K/AKT signaling pathway by encoding SEMA4B-211aa." (PMID 39402211, 2025). "Similarly, both circSEMA4B and its encoded peptide, SEMA4B-211aa, manifest at lower levels in breast cancer (BC) and function as tumor suppressors both in vivo and in vitro." (PMID 38877495, 2024). "In breast cancer, a few studies have shown that circRNAs encode peptides, including circ-EIF6, which encodes EIF6-224aa; circ-HER2, which encodes HER2-103; and circSEMA4B, which encodes SEMA4B-211aa, which reportedly participate in the progression and drug resistance of tumors." (PMID 38755678, 2024). "SEMA4B‐211aa and EIF6‐224aa have been confirmed to regulate the formation and development of breast cancer." (PMID 36644969, 2023).
lung carcinoma (8 papers, 2019 to 2023). "Semaphorin 4B (SEMA4B) has been implicated in lung cancer as both a potential oncogene and tumour suppressor." (PMID 37685898, 2023). "Although aberrant SEMA4B activity has been observed in multiple types of malignancies, the underlying roles of SEMA4B in lung cancer are still uncertain." (PMID 35676688, 2022). "In addition, a query of the human protein atlas database revealed that the gene was associated with poor prognosis in lung cancer; thus, we suggest that further experiments might be required to verify the role of SEMA4B." (PMID 34109216, 2021). "Further study found that SEMA4B silencing suppressed the proliferation of lung cancer cells both in vitro and in vivo." (PMID 35676688, 2022). "In lung cancer, SEMA4B initially recognized for its ability to stimulate cell motility." (PMID 35676688, 2022). "The CCK8 and Edu assay and plate cloning formation assay shown that SEMA4B knockdown by transfection of cells with siRNA could inhibit cell proliferation and reduce colony formation of lung cancer cells in vitro." (PMID 35676688, 2022). "We found that SEMA4B could significantly promote lung cancer cell proliferation both in vivo and in vitro." (PMID 35676688, 2022). "Sema4B overexpression also reduced hypoxia-induced invasion of lung cancer cells." (PMID 33858502, 2021). "Importantly, bioinformatic studies indicated SEMA4B may be an immune-related biomarker that could improving the prediction of prognosis in lung cancer." (PMID 35676688, 2022). "However, the role of Semaphorin 4B (SEMA4B) in lung cancer remains unclear." (PMID 35676688, 2022). "Previous work demonstrated that the SEMA4B and DCBLD2 interaction is involved in the regulation of the motility of lung cancer cell lines." (PMID 34522794, 2021). "However, to our knowledge, the role of SEMA4B in lung cancer immunotherapy has not been thoroughly demonstrated, especially under in vivo conditions." (PMID 35676688, 2022).
glioma (5 papers, 2015 to 2025). A benign or malignant brain and spinal cord tumor that arises from glial cells (astrocytes, oligodendrocytes, ependymal cells). "Nevertheless, it also revealed that certain splice variants of Sema4B are important for the ability of glioma cells to grow as individual clones." (PMID 29311693, 2018). "One cannot ignore the possibility that a unique splice variant of the human gene is necessary for the activity of Sema4B in gliomas." (PMID 29311693, 2018). "In glioma, downregulation of SEMA4B inhibited U87 cell proliferation, clone formation and migration in vitro and attenuated tumorigenicity in vivo." (PMID 35676688, 2022). "Here, we present the case of Sema4B as a possible regulator in glioma biology and demonstrate an approach to differentiate between compensatory mechanisms and off-target effects using combined shRNA over CRISPR-Cas9 methodology." (PMID 29311693, 2018). "While looking for new genes involved in glioma tumorigenic phenotype we decided to test one of the members of the semaphorin family, namely Sema4B." (PMID 29311693, 2018). "Two lines of glioma cells (U87-MG and A172) were tested; in both cases Sema4B was up-regulated in response to hypoxia." (PMID 29311693, 2018). "This approach is demonstrated by testing a possible role for Sema4B in glioma biology, in which our results implicate Sema4B as having a critical function." (PMID 29311693, 2018). "To study the biological effect of Sema4B in glioma cells, we tested the effect of its depletion using the well-established shRNA approach." (PMID 29311693, 2018). "To validate the specificity of the effects of the shRNA on the glioma cells, we attempted to use a rescue strategy, in which we infected the same cells with both the mouse Sema4B cDNA and shRNA directed at the human Sema4B." (PMID 29311693, 2018). "To begin testing the role of Sema4B in gliomas, we examined the expression of Sema4B in different glioma lines." (PMID 29311693, 2018). "All the same, the exact role of Sema4B in glioma biology will need further investigation." (PMID 29311693, 2018). "Thus, the case of Sema4B in glioma as presented here should be considered as a warning to the scientific community to critically read publications that rely mostly on RNA interfering strategies." (PMID 29311693, 2018). "The case of Sema4B function in glioma presented here is complex." (PMID 29311693, 2018). "We have recently shown that Sema4B has a role in astrocyte (a type of glial cell) proliferation and therefore decided to test whether this protein has a function in glioma formation." (PMID 29311693, 2018). "Indeed, Sema4B protein and mRNA are expressed by all glioma cell lines tested, although these lines express Sema4B at different levels." (PMID 29311693, 2018). "To further characterize the effects of Sema4B depletion, we repeated the shRNA treatment with two glioma lines (U87-MG and G55TL, a glioma stem cell line) and monitored the number of cells for up to 168 h (in U87-MG) or up to 96 h (in G55TL)." (PMID 29311693, 2018). "Among the Sema4 genes, SEMA4B and SEMA4C showed mild expression increase in gliomas and glioblastoma subtypes, while the other Sema4s appeared mainly unchanged or downregulated." (PMID 25762646, 2015). "Regardless of whether Sema4B was intact or lost within the glioma CRISPR clones (in control clones or deleted ones), all lines responded similarly when treated with sh-SM4Bs (one infecting unit/cell as determined by testing parental U87MG)." (PMID 29311693, 2018).
gastric cancer (4 papers, 2019 to 2025). A primary or metastatic malignant neoplasm involving the stomach. "This study showed that three mRNAs (SPINK7, PPL, and SEMA4B) and two miRNAs (miR140-5p and miR301a) were significantly downregulated in gastric cancer patients." (PMID 40429589, 2025). "A previous study on salivary exRNA biomarkers showed that three mRNAs (SPINK7, PPL, and SEMA4B mRNAs) and two miRNAs (miR140-5p and miR301a) were significantly down-regulated in gastric cancer patients compared with healthy individuals in a Korean population." (PMID 40429589, 2025). "For example, in a study, 5 exRNAs, including 3 mRNAs (SPINK7, PPL, and SEMA4B) and 2 microRNAs (MIR140-5p and MIR301a), showed downregulation in gastric cancer (GC)." (PMID 35948986, 2022).
lung adenocarcinoma (4 papers, 2021 to 2025). A carcinoma that arises from the lung and is characterized by the presence of malignant glandular epithelial cells. "By differential expression analysis and LASSO logistic regression analysis we constructed an 8-gene (IKBKB, LTBR, MIF, PPARD, PPIA, PSME3, S100A6, SEMA4B) based risk score model to predict lymph node metastasis in lung adenocarcinoma." (PMID 34109216, 2021). "SEMA4B is a transmembrane glycoprotein that has been reported to be overexpressed in lung adenocarcinoma, which has been correlated with poor prognosis." (PMID 37173939, 2023). "In the present study, the possible mechanism by which SEMA4B affected the tumor growth and microenvironment of lung adenocarcinoma (LUAD) were investigated." (PMID 35676688, 2022). "Recently, SEMA4B was indicated as an predictor of lymph node metastasis in lung adenocarcinoma." (PMID 35676688, 2022).
laryngeal squamous cell carcinoma (3 papers, 2022 to 2023). A squamous cell carcinoma that arises from the larynx. "MiR-204-5p hampered the proliferation and invasion of laryngeal squamous cell carcinoma by reducing the abundance of SEMA4B." (PMID 36550514, 2022). "For instance, SEMA4B expression in laryngeal squamous cell carcinoma (LSCC) was significantly upregulated and exogenous transforming SEMA4B confers LSCC cell growth traits." (PMID 35676688, 2022).
acne (2 papers, 2018 to 2021). An inflammatory process of the sebaceous glands which is characterized by comedones, nodules, papules and/or pustules on the skin. "There is strong evidence that the acne association signal at this locus and a skin eQTL for SEMA4B colocalise (Pcoloc = 0.98), with the allele that ablates the TP63-binding motif associated with a reduction in SEMA4B expression in skin and conferring protection against severe acne." (PMID 30542056, 2018). "In addition, while the role of SEMA4B in acne pathogenesis is uncertain, it is known to be involved in immune responses and downregulates the secretion of IL-4 and IL-6 in basophils." (PMID 33849530, 2021). "Thus, it is possible that SEMA4B may also play a role in acne-related immune processes." (PMID 33849530, 2021).
behavioral disorders (2 papers, 2017 to 2025). "In addition, differentially methylated CG dinucleotides in LRP2BP, TOP1, NOSIP, and SEMA4B were associated with intellectual disability, behavioral disorders, disorders of psychological development, and schizophrenia spectrum disorders, respectively." (PMID 39460848, 2025).
injury (2 papers, 2015 to 2020). Damage inflicted on the body as the direct or indirect result of an external force, with or without disruption of structural continuity. "Phosphorylation of the Semaphorin 4b cytoplasmic domain has been shown to play important roles in reactive astrogliosis, with Sema4b-/- mice showing defects in the migration of reactive astrocytes to damaged regions following experimental brain injury." (PMID 33031376, 2020). "Sema4B is a transmembrane type 4 semaphorin, which has been suggested to be expressed in astrocytes; however, the role of the Sema4B gene in astrocytes following brain injury is not known." (PMID 26464987, 2015).
non-small cell lung carcinoma (2 papers, 2021). A group of at least three distinct histological types of lung cancer, including non-small cell squamous cell carcinoma, adenocarcinoma, and large cell carcinoma. "SEMA4B has been shown to inhibit the invasion of non-small cell lung cancer through the PI3K signaling pathway." (PMID 34109216, 2021).
cardiomyopathy (1 paper, 2014). A disease of the heart muscle or myocardium proper. "The lower levels of VEGF-A protein and Sema4b mRNA in hearts of TAC severe mice compared with control mice are consistent with the more severe cardiomyopathy phenotype in these animals." (PMID 24587330, 2014).
colon cancer (1 paper, 2025). "The results showed that C17orf57 and SEMA4B were positively correlated with MSI, while RHOB presented a negative correlation in colon cancer." (PMID 40574864, 2025).
ischemic stroke (1 paper, 2022). A stroke disorder caused by obstruction of blood flow to the brain, due to thrombotic (local blood clot formation) or embolic (due to a blood clot or other material traveling from another site) event. "Semaphorin 4B (Sema4B) serves as an astrocyte receptor to regulate astrogliosis after ischemic stroke." (PMID 35350431, 2022). "We can speculate that Sema4B serves as an astrocyte receptor may regulate astrogliosis after ischemic stroke." (PMID 35350431, 2022). "In-depth study of Sema4B may provide potential target for ischemic stroke treatment." (PMID 35350431, 2022).
multiple sclerosis (1 paper, 2025). A progressive autoimmune disorder affecting the central nervous system resulting in demyelination. "This receptor is also involved in the Sema4B-mediated inflammation in microglia/macrophages, the Sema4D-mediated cartilage destruction, the Sema4A-induced secretion of IL-17 by CD4+ T cells of systemic sclerosis patients and the Sema4D-mediated inflammation in a mouse model of multiple sclerosis." (PMID 40598553, 2025).
myopia (1 paper, 2019). "Our study identified methylation differences in the semaphorins, such as SEMA3F, SEMA4B, SEMA4C and SEMA5A that were significantly associated with myopia." (PMID 30858441, 2019).
Obesity (1 paper, 2023). Accumulation of substantial excess body fat. "Future studies will be required to determine whether the Sema4B pathway is actionable for the improvement of metabolic health, for instance to enhance adipocyte recruitment to mitigate the detrimental metabolic effects associated with obesity or to enhance thermogenesis." (PMID 37121509, 2023). "To understand if Sema4B may play a role in obesity and adipose tissue thermogenesis, we evaluated mRNA expression of Sema4B and its receptors (plexins and neuropilins) in adipose tissues from obese mice and lean mice exposed to different ambient temperatures." (PMID 37121509, 2023). "Our human data are similarly complex, showing that the levels of candidate Sema4B receptors/co-receptors but not necessarily Sema4B itself are elevated during obesity and downregulated in obese subjects following weight loss." (PMID 37121509, 2023). "To investigate if this novel pathway mediated by Sema4B cleavage by ADAM17 in adipocytes could have an impact in human obesity, we measured the mRNA levels of SEMA4B, PLEXIN (PLXN)B1 and 2, NEUROPILIN (NRP) 1 and 2, ADAM17, and of its known critical regulator iRHOM2 in human adipose tissues." (PMID 37121509, 2023).
osteoarthritis (1 paper, 2025). A noninflammatory degenerative joint disease occurring chiefly in older persons, characterized by degeneration of the articular cartilage, hypertrophy of bone at the margins and changes in the synovial membrane. "Fibroblast-like synoviocytes (FLS) from patients with osteoarthritis (OA) and RA and 3D synovium micromasses, formed by RA FLS and RA monocytes, were stimulated with Sema4B and TNF-α alone and in combination." (PMID 40598553, 2025).
psoriasis (1 paper, 2022). An autoimmune condition characterized by red, well-delineated plaques with silvery scales that are usually on the extensor surfaces and scalp. "In addition, Sema4B could inhibit basophil-mediated Th2 skewing and contributes to the developing Th1/Th2 imbalance in psoriasis." (PMID 35054504, 2022).
renal cell carcinoma (1 paper, 2022). "Besides, overexpression of SEMA4B was observed in renal cell carcinoma and contributed to the tumor progression and poor prognosis." (PMID 35676688, 2022).
Sepsis (1 paper, 2025). Sepsis is defined as life-threatening organ dysfunction caused by a dysregulated host response to infection. "The relative expression levels of GNMT, SEMA4B, FURIN, and RNASE2 were significantly lower in the sepsis group than those in the control group." (PMID 40526611, 2025).
Stroke (1 paper, 2015). Sudden impairment of blood flow to a part of the brain due to occlusion or rupture of an artery to the brain. "In contrast, LCN2, an iron-trafficking protein shown to be specifically induced in astrocytes following inflammation and stroke, was also induced following stab wound injury, but activation in Sema4B−/− mice was ∼1.5 times higher compared to that in Sema4B+/− mice." (PMID 26464987, 2015).